LAMC1 (laminin subunit gamma 1)
Diseases named in the same sentence as LAMC1 in open-access papers (continued):
Sharing a sentence is not in itself a finding about the gene and the disease.
tumor (49 papers, 2014 to 2025). "Notable examples include ZEB1, a major inducer of EMT, as well as LAMC1, an extracellular matrix protein associated with tumor invasion and metastasis." (PMID 37117180, 2023). "We confirmed that TGFβ1 acted on tumor cells, causing a series of changes: upregulation of LAMC1; phosphorylation of NF‐κB; secretion of CXCL1; phosphorylation of STAT3 in CAF; and finally, the induction of the formation of iCAF, that is, tumor‐promoting CAF." (PMID 34218518, 2021). "As in other types of tumors, high LAMC1 expression can promote ESCC tumor cell proliferation and migration and is associated with a poor prognosis; thus, LAMC1 can be used as a biomarker." (PMID 34218518, 2021). "And LAMC1 was associated with feature ‘Rectlike’ and ‘deviation ratio of tumor and normal thyroid gland’ (p<0.001; p<0.001); THBS1 was correlated with ‘minimum calcification area’ (p<0.001)." (PMID 34268116, 2021). "Many over-expressed genes in tumor-associated T cells were involved in tissue remodeling (e.g., Col1a1, Col4a1, Fn1, Lamc1, Mmp2, Mmp10, Timp3) and cell motility/adhesion (Rhoc, Itga1, Itgav)." (PMID 31477729, 2019). "Notably, LAMC1 expression increased with the stage in most tumors, suggesting that high LAMC1 expression is associated with tumor progression." (PMID 38678297, 2024). "We speculate that tumours expressing high levels of LAMC1 may be more susceptible to H-1PV infection." (PMID 34158478, 2021). "Studies suggest that LAMC1 overexpression in CRC enhances tumor cell survival and chemoresistance by activating integrin/FAK signaling pathways." (PMID 40496862, 2025). "It played a key role in shaping the tumor microenvironment via the LAMC1-(ITGA3-ITGB1) signaling pathway." (PMID 40589640, 2025). "Next, we examined differential expression of LAMC1 in patients with each tumor type in accordance with age and the tumor stage in TCGA database." (PMID 38678297, 2024). "As an ECM component, the role of LAMC1 in the tumor hypoxia microenvironment and ECM remodeling is worth further study." (PMID 38678297, 2024). "Laminin subunit gamma-1 (LAMC1) is a major extracellular matrix molecule involved in the tumor microenvironment." (PMID 38678297, 2024). "Some studies have reported on the role of LAMC1 in tumor biology, suggesting that high expression of LAMC1 promotes the proliferation, invasion, and metastasis of tumor cells." (PMID 38678297, 2024). "LAMC1 is also involved in a variety of biological and pathological processes including tumor cell development, invasion, and metastasis." (PMID 37138286, 2023). "The significance of integrin signaling for PFA tumor progression is further suggested by the recurrent transcriptional activation of LAMC1 in PFA relapse tumors, which frequently harbor gains of chromosome 1q." (PMID 37085539, 2023). "Immunohistochemical staining results revealed that subcutaneous tumor tissue constructed by LAMC1 knockout cell line had up-regulated expression of E-cadherin, down-regulated vimentin and Ki67 expression." (PMID 35541892, 2022). "The correlation between LAMC1 expression and these molecules suggests a possible mechanism, signaling pathway, and prognostic value for LAMC1 in tumor immunity." (PMID 36188228, 2022). "Bioinformatic analysis using the gene expression profiling interactive analysis tool showed that LAMC1 is differentially expressed (down- and upregulated in comparison with paired normal tissues) across the various tumours." (PMID 34158478, 2021). "This study explored the carcinogenic effect of LAMC1 in ESCC from two aspects: the direct effect on tumor cells and indirect effect through the TME, especially CAF." (PMID 34218518, 2021). "Consistent with the results of the in vitro experiments, the tumor volume and weight in the LAMC1‐overexpression group were significantly increased compared with those in the control group." (PMID 34218518, 2021). "The proliferation and migration of tumor cells was promoted by LAMC1 via the Akt/NF‐κB/MMP9‐MMP14 pathway." (PMID 34218518, 2021).
tumor (continued). "LAMA1/A5 and LAMC1 were significantly and negatively correlated with various tumor immune infiltrates (TILs), especially with dendritic cells, CD8+ T cells or neutrophil." (PMID 34512203, 2021). "The values of the radiomic features ‘Rectlike’ and ‘deviation ratio of tumor and normal thyroid gland’ were significantly correlated with the expression of LAMC1 (r=-0.658, p<0.001; r=0.715, p<0.001)." (PMID 34268116, 2021). "LAMC1 directly promoted the proliferation and migration of tumor cells, mainly via Akt–NFκB–MMP9/14 signaling." (PMID 34218518, 2021). "This study focused on exploring the tumorigenic mechanism of LAMC1 and its role in the microenvironment, especially in the interaction of tumor cells and CAF." (PMID 34218518, 2021). "LAMC1 is known to be involved in tumor cell proliferation, growth, angiogenesis, invasion and migration." (PMID 31450586, 2019). "As an example miR-205 is known to be down-regulated in TNBC55, it is a known tumour-suppressor-miR that targets E2F1, LAMC1, suppresses cell proliferation, cell cycle and tumour growth." (PMID 26537449, 2015). "Finally, ECM and fibrosis-related molecules (COL1A1, COL4A1, COL6A3, fibronectin, and LAMC1) were elevated, closely mimicking the desmoplastic tumor microenvironment of HCC." (PMID 41149589, 2025). "Notably, for other tumor types, LAMC1 has already been shown to be involved in tumor cell invasion and metastasis." (PMID 37085539, 2023). "Moreover, LAMA1/A5 and LAMC1 were significant negatively correlated with tumor immune infiltrates in OV, especially with dendritic cells, CD8+ T cells or neutrophil." (PMID 35612641, 2022). "Taken collectively, these findings suggest that FSTL3 and LAMC1 are involved in tumor biology and targeting LINC00922 may be an effective therapy in GC patients." (PMID 35511773, 2022). "Furthermore, miR-424-5p repressed the LAMC1-mediated Wnt/β-catenin signaling pathway, thus inhibiting angiogenesis, migration of human umbilical vein endothelial cells (HUVECs), and tumor development." (PMID 36032078, 2022). "It is worth mentioning that CXCR2 inhibitors showed a better response to rCXCL1 on CAF than tumor CM, suggesting that LAMC1 may also influence other factors contributing to the formation of iCAF." (PMID 34218518, 2021). "In summary, we identified the dual mechanism by which the upregulation of LAMC1 by TGFβ in tumor cells not only promotes ESCC proliferation and migration, but also indirectly induces carcinogenesis by stimulating CXCL1 secretion to promote the formation of iCAF." (PMID 34218518, 2021). "LAMC1 is involved in many carcinogenic effects within tumor cells." (PMID 34218518, 2021). "Whether LAMC1 influences the heterogeneity of CAF by affecting other factors or exosome secretion in tumor cells may require further study." (PMID 34218518, 2021). "miR-375-3p may act as a tumor suppressor by targeting LAMC1 in HNSCC." (PMID 33968726, 2021). "LAMC1 (Laminin Subunit Gamma 1) is a key component of the extracellular matrix (ECM) and plays a crucial role in tumor progression, invasion, and metastasis by modulating cell adhesion, migration, and epithelial-to-mesenchymal transition (EMT)." (PMID 40496862, 2025). "The expression levels of TFRC, LAMC1, PLK1, TYMS, and TSSK6 were significantly higher in tumor tissues while TNFSF14 exhibited higher expression levels in normal tissues." (PMID 40496862, 2025). "Through Akt–NF-κB–MMP-9/14 signalling, LAMC1 promoted the multiplication, infiltration of tumour cells, increased CXCL1 production and enhanced the development of iCAFs, resulting in enhanced tumour growth both in vitro and in vivo." (PMID 37927475, 2023). "Interestingly, the anti-correlation is strongest when the LGALS1 and LAMC1 expression levels are analysed together, suggesting that their combined expression analysis may better predict the success of H-1PV infection against a certain tumour." (PMID 35632759, 2022).
tumor (continued). "Our analysis shows that upregulation of LAMC1 and LAMB1 gene expression is a marker of poor prognosis for certain tumours." (PMID 34158478, 2021). "In vivo, we established a xenograft tumor mouse model by subcutaneous inoculation or intravenous tail injection of KYSE30 cells transfected with shLAMC1, sh‐vec, overexpressed LAMC1 and control vector." (PMID 34218518, 2021). "In conclusion, the overexpression of LAMC1, upregulated by TGFβ1 via SMAD4/SP1 synergistic activation, promoted the proliferation and migration of tumor cells mainly via NF‐κB/MMP9‐MMP14." (PMID 34218518, 2021). "Here, we demonstrate the tumour cell-specific expression of laminin chains α5, β1 and γ1 (LAMA5, LAMB1 and LAMC1 respectively) in orthotopic human liver metastases from mice and the deposition of these laminin chains within the tumour stroma." (PMID 31064120, 2019). "Similarly, LAMC1 showed a significant increase (P < 0.05), while TNFSF14 was significantly downregulated in tumor tissues (P < 0.0001)." (PMID 40496862, 2025). "The predominant predicted tumor-to-microglia interactions in this model were driven by tumor junctional adhesion molecule (JAM) and extracellular matrix (ECM) ligands, such as collagens (e.g., COL4A2, COL6A3) and laminins (e.g., LAMA3, LAMC1)." (PMID 39372744, 2024). "To explore whether ESCC tumor cell‐secreted CXCL1, upregulated by LAMC1, influences CAF heterogeneity, we performed mRNA‐seq in the following cells: CAF treated with PBS; CAF with recombinant CXCL1 (rCXCL1) treatment; CAF with sh‐vec CM treatment." (PMID 34218518, 2021). "Human LAMA5, LAMB1 and LAMC1 transcripts were identified in orthotopic metastases, a finding supported by immunohistochemical analysis demonstrating the expression of the human LAMA5 protein in these tumours." (PMID 31064120, 2019). "Indeed, the tumor cores (L and LB) were found to express numerous pEMT genes at significantly greater levels than the TME, including the laminins (LAMC1, LAMC2, LAMA3), integrins (ITGA2, ITGB1, ITGAV), and inflammatory and neutrophil-attracting chemokines (CXCL8, CXCL1)." (PMID 36216799, 2022). "Substantial differences between tumor and neighboring healthy cortex were found in both interstitial matrix proteins, such as collagen 6 (COL6A1, COL6A2, COL6A3), and basement membrane components such as collagen 4 (COL4A1, COL4A2) and laminins (LAMA5, LAMA4, LAMB1, LAMB2, LAMC1)." (PMID 34884982, 2021). "Strong immunoreactivity of TFRC, LAMC1, PLK1, and TYMS was observed in tumor tissues, whereas weak or no staining was observed in normal tissues." (PMID 40496862, 2025).
infection (8 papers, 2012 to 2025). The state of being infected such as from the introduction of a foreign agent such as serum, vaccine, antigenic substance or organism. "In agreement with published results, infection of HeLa LAMC1 KD cells presented a 40% reduction in cell-associated H-1PV genomes in comparison with Control cells." (PMID 35632759, 2022). "“PI3K/AKT” and “Integrin signalling” were significant in IPA of the IA-H/S data set and several infection-associated genes involved in integrin signalling, possess differences in the number of TashAT2 binding motifs between the two genomes (LAMC1, ACTA2, ITGA4 and ITGB5)." (PMID 35061738, 2022). "A significant decrease in H-1PV infection was observed in LAMC1 KD cell line compared with parental HeLa cells." (PMID 34158478, 2021). "Our discovery that LAMC1 is a key determinant of H-1PV infection raises the possibility of using LAMC1 and possibly other laminin chains as biomarkers to predict the outcome of H-1PV-based therapies." (PMID 34158478, 2021). "Recently, the first LAMC1 sub-network modulated by invasive trypomastigotes during the early process of infection was elucidated." (PMID 23133440, 2012). "ERK1/2 was used as one seed mode, since T. cruzi gp83 activates ERK1/2 in cells to up-regulate the LAMC1 expression and infection." (PMID 23133440, 2012). "This increase in cellular infection was seen as over-attachment and entry of trypomastigotes into human cells over-expressing LAMC1, under the influence of gp83 ligand, resulting in high parasite multiplication at 72 h." (PMID 23133440, 2012). "T. cruzi gp83, a ligand that mediates the attachment of trypanosomes to cells to initiate infection, up-regulates LAMC1 expression to enhance cellular infection." (PMID 23133440, 2012). "Exposure of gp83 ligand to human cells increases the level of LAMC1 transcripts and its expression in mammalian cells, leading to an increase in cellular infection by T. cruzi." (PMID 23133440, 2012). "Given that laminins containing the γ1 chain play determinant roles in H-1PV attachment at the cell surface as well as in H-1PV cell entry, we asked whether siRNA-mediated silencing of LAMC1 in LGALS1 KO cells would further decrease H-1PV infection." (PMID 35632759, 2022). "The regulation of infection by the gp83 ligand represents a parasite escape mechanism in which invasive trypomastigotes release gp83 to efficiently gain entry into human coronary artery smooth muscle (HCASM) cells by manipulating LAMC1, which is the most abundant isoform of laminin in humans." (PMID 23133440, 2012). "On the other side, triggering gp83 receptors in the cell via ERK1/2 cross-talk with the THBS1 sub-network, also enhances cellular infection and cross-talk at a distance with LGALS3, which also recruit parasites via Tc45 mucin, and LAMC1." (PMID 23133440, 2012). "Infective trypomastigotes use Tc85 to interact with laminin, p45 mucin to interact with LAMC1 through galectin-3 (LGALS3), a human lectin, and calreticulin (TcCRT) to interact with TSB1 to enhance cellular infection." (PMID 23133440, 2012). "The result of this analysis showed that the only ECM proteins, LAMC1 and THBS1, were important in the early infection process." (PMID 23133440, 2012). "Infective trypomastigotes up-regulate the expression of laminin γ-1 (LAMC1) and thrombospondin (THBS1) to facilitate the recruitment of trypomastigotes to enhance cellular infection." (PMID 23133440, 2012). "Since the T. cruzi gp83 ligand remodels the ECM by up-regulating the expression of LAMC1, together with the report that T. cruzi presents laminin receptors on its surface, indicates that the parasite exploits LAMC1 to navigate through the ECM, recruit trypanosomes and facilitate infection." (PMID 23133440, 2012).
adenocarcinoma (1 paper, 2016). A common cancer characterized by the presence of malignant glandular cells. "The clustering also highlighted a set of proteins that was almost solely present in control tissue of adenocarcinoma patients, including FANCJ, CCAR2, AGRIN, and LAMC1." (PMID 26930711, 2016).
cardiac diseases (1 paper, 2022). "However, cardiac diseases were independent of the functions of LAMC1, COL4A3, and ATP2C2." (PMID 35924220, 2022).
CNS tumors (1 paper, 2024). "However, a relatively high expression level of LAMC1 was found in CNS tumors." (PMID 38678297, 2024).
psychiatric disorder (1 paper, 2021). A disorder characterized by behavioral and/or psychological abnormalities, often accompanied by physical symptoms. "Future research should consider whether LAMC1 and the network of genes it interacts with could be used to inform alternative ways of promoting neurogenesis and hippocampal volume in psychiatric disorder patients." (PMID 34718328, 2021).
LAMC1 also shares sentences with these, for which no sentence is quoted: premature ovarian failure (3 papers); cutaneous squamous cell carcinoma (2); endometrioid carcinoma (2); Alzheimer disease (1); amoebiasis (1); aneurysm (1); Arrhythmia (1); atrial fibrillation (1); autism (1); benign colon neoplasm (1); Cerebral ischemia (1); cervical intraepithelial neoplasia (1); clear cell carcinoma (1); dementia (1); dilatation (1); Ewing sarcoma (1); gastric tumors (1); gynecologic cancers (1); hepatitis C (1); human papillomavirus infection (1); Hypertension (1); kidney disease (1); kidney failure (1); liver cancer (1); lung adenocarcinoma (1); lung disease (1); migraine disorder (1); myeloma (1); myopathy (1); non-small cell lung carcinoma (1).
A further 13 diseases each share a sentence with LAMC1 in 1 paper.